HIF1A (hypoxia inducible factor 1 subunit alpha)
Diseases named in the same sentence as HIF1A in open-access papers (continued):
Sharing a sentence is not in itself a finding about the gene and the disease.
tumor (continued). "The transcription factor HIF‐1α is involved in tumour angiogenesis by regulating the transcriptional induction of angiogenesis‐related genes, such as VEGF, that contain HRE cis‐acting elements within their promoters." (PMID 34318593, 2021). "HIF-1α is not only a key nuclear transcription factor in the tumor hypoxia, but also an upstream transcriptional regulator of genes associated with tumor cell proliferation, apoptosis, neovascularization, invasion and metastasis." (PMID 35004677, 2021). "In mice injected with HIF-1α depleted A549 cells, impaired tumor vascularization and increased necrotic area was observed." (PMID 33445709, 2021). "The hypoxic microenvironment of the tumor induces the expression of Hypoxia-inducible factor (HIF)-1α, which leads to transcriptional upregulation of VEGF-A in the cancer cells." (PMID 34613483, 2021). "Contrary to its effect in tumor tissue, HIF-1α is unable to induce an effective angiogenic response in adipose tissue hypoxia." (PMID 33920379, 2021). "The decrease in SDH levels in tumor cells results in the accumulation of succinate, which increases the stability of the transcription factor HIF1α and reprograms cell metabolism to a glycolytic state." (PMID 34654454, 2021). "Piezo1 knockdown can reduce the expression of Piezo1 and HIF‐1α in GC cells and omentum metastatic tumour tissues, thereby effectively inhibiting the EMT process of GC cells as well as the peritoneal cavity implantation and metastasis of GC cells in nude mice." (PMID 33439514, 2021). "HIF1α (hypoxia inducible factor-1) is a key regulator of many signals in tumor occurrence, development, and chemotherapy resistance." (PMID 33440739, 2021). "It is well known that hypoxic in tumor microenvironment by HIF-1α activation can promote angiogenesis, tumor growth, metastasis, and cancer resistance." (PMID 34825004, 2021). "In a mouse model of mammary tumorigenesis, inactivation of BNIP3 resulting in defective mitophagy was shown to elevate ROS production and normoxic HIF-1α stabilization, which accelerated tumor progression to metastasis." (PMID 34490076, 2021). "HBx was shown to interact with HDAC1 and HDAC2, and HBx-induced stabilization of hypoxia-inducible factor 1 alpha (HIF-1α), a key regulator in tumor growth, angiogenesis and metastasis of HCC, involved deacetylation by HDAC1." (PMID 34361112, 2021). "In HCC, HIF-1α functions as an oncogene, mediating cell proliferation, tumor chemoresistance, metastasis, glycolysis and angiogenesis." (PMID 34540836, 2021). "Hypoxic conditions in a cancer microenvironment stimulate the angiogenesis required for tumor growth by inducing the expression of hypoxia-inducible factor-1 alpha (HIF-1α)." (PMID 33917793, 2021). "Since the osteogenic niche is reduced in the Hif1α−/− PyMT+ mice, as indicated by the reduction in bone volume, the shrinkage of suitable niches available for tumor cell engraftment in bone may cause a larger portion of the metastatic tumor cells to engraft in the lung instead." (PMID 34556788, 2021). "In this regard, efforts have been made to develop anti-cancer therapeutics specifically targeting the HIF-1α regulation pathway, which is crucial for the survival of tumour cells." (PMID 34829672, 2021). "In many tumour cells, the expression of glycolytic enzymes is induced by hypoxia by activating HIF-1α." (PMID 34298795, 2021). "This latter point is further confirmed by an important study showing how the specific inhibition of HIF-1α expression on NK cells can deeply change their behavior in the tumor hypoxic environment." (PMID 34696251, 2021). "We present data showing that CaO2-MNPs treatment in TNBC reduces hypoxic stress in tumor evident by decreased HIF-1α expression and increased doxorubicin-sensitivity in vivo." (PMID 33546453, 2021).
tumor (continued). "Together, our data strongly argue that therapeutic strategies disrupting HIF-1α/HIF-1β dimerization would be able to switch the tumor microenvironment from immunosuppressive to immunopermissive for the infiltration of NK and CD8+ effector T cells." (PMID 34155342, 2021). "The stabilization of HIF1α leads to the expansion of the GSC population within the bulk of the tumor, which is, in part, mediated by the extracellular signaling related kinase (ERK) and the PI3K/AKT pathways." (PMID 33391498, 2021). "In this regard, it has been identified that tumor-associated macrophages (TAMs)-derived exosomes transfer HISLA to breast cancer cells, to prevent HIF-1a degradation, thus promoting aerobic glycolysis." (PMID 34078376, 2021). "miR-217 directly targets HIF-1α, so circRNA_100859 was able to inhibit the tumor-suppressive effects of miR-217." (PMID 34162394, 2021). "Higher HIF-1α (HIF-1αhigh) expression was observed in tumor tissues with higher TARBP2 (TARBP2high) levels, and vice versa." (PMID 35008634, 2021). "HIF-1α also up-regulates the expression of pH regulator MCT-1 in tumor cells, regulating pH homeostasis." (PMID 33718176, 2021). "IHC showed that the tumour tissues of the HIF1α-ko or HIF2α-ko individual group had lower expression of Ki67 and Bcl2 than the control and the dual HIF1α and HIF2α knockout group." (PMID 33986256, 2021). "Reactive species (RS), which are produced during tumor irradiation, are involved in the stabilization of HIF-1α and HIF-1α-regulated mRNA." (PMID 34829640, 2021). "GEPIA analysis showed that HIF1A expression level was noticeably increased in SC tumor tissues (red, T) than that in normal tissues (gray, N)." (PMID 34621671, 2021). "In line with this, in areas of hypoxia, TAMs upregulate HIF-1α, which enables migration and survival, suggesting a feedback loop and signaling between tumor cells and TAMs that regulate their metabolic phenotype." (PMID 33968034, 2021). "Hypoxia-inducible factor 1-alpha (HIF1A) is an oxygen-dependent transcriptional activator that plays key roles in tumor angiogenesis and mammalian development." (PMID 33777163, 2021). "When NK cells upregulate HIF-1α in response to tumor hypoxia, they fail to increase their expression of major activating surface receptors NKp46, NKp30, NKp44, and NKG2D and degranulate in response to cytokines." (PMID 33670082, 2021). "Studies have reported that the presence of nutrient and oxygen starvation in the TME initiates malignant transformation, tumour progression, angiogenesis, and metastasis and affects therapy response via mediation of the ROS/HIF-1α-axis." (PMID 34829672, 2021). "NF-κB-signaling activation can also stimulate HIF-1α expression, thereby enhancing the hypoxic adaptation of tumor cells and the early survival of metastasis-initiating cells." (PMID 33962660, 2021). "PDAC is known for enhanced HIF-1α levels, which maintain a functional relationship between tumor cells and stromal fibroblasts by upregulating the expression and secretion of Sonic hedgehog." (PMID 33546284, 2021). "Namely, HIF-1α crosstalk with TGF-β signaling to promote tumor progression by increased expression of c-Myc and PKM2 under hypoxia through changing Smad partners in cancer cells." (PMID 34930376, 2021). "In vitro, DR2 interacts with von Hippel-Lindau (VHL) in the nucleus to reduce ubiquitination mediated HIF1a degradation and enhance epithelial-mesenchymal transformation of tumor cells." (PMID 34988010, 2021). "HIF-1α has been reported to participate in regulating radiotherapy resistance by initiating glycolytic tumor metabolism in various cancers." (PMID 33664256, 2021). "A hypoxic tumor microenvironment promotes HIF1-α-induced EMT and thus enhances the invasive and migratory abilities and VM in tumors." (PMID 33850110, 2021). "Mechanistically, mutationally activated KRAS stabilizes HIF-1α, which drives the production of CSF2 and lactate in tumor cells." (PMID 33833221, 2021).
tumor (continued). "Collectively, all these results demonstrated that NRP1 expression was induced by HIF-1α in the hypoxic tumor microenvironment." (PMID 33850110, 2021). "Upregulation of hypoxic-induced factor-1α (HIF-1α) leads to the activation of various factors that contribute to the increased drug resistance, proliferation, and migration of tumor cells." (PMID 33990544, 2021). "Treatment with the mTORC1 agonist MHY1485 led to partial recovery of the reduced HIF-1α expression and invasiveness of Prak-deleted tumor cells." (PMID 33741957, 2021). "NAC is reported to inhibit hypoxia inducible factor 1-alpha (Hif1a) stabilization and perturb the hepato-cellular xeno-graft tumor." (PMID 33477494, 2021). "This is the first study to elucidate the biological functions of the IGF2BP3/HIF1A axis in hypoxia-induced adaptive responses and hypoxia-triggered tumor malignant progression in SC." (PMID 34621671, 2021). "In CRC, miR-206 acts on the Met/ERK/Elk-1/HIF-1α/VEGF-A pathway to inhibit tumour angiogenesis, and CCL19 can drive this process by promoting miR-206 expression." (PMID 33865381, 2021). "Mechanistically, the generation of 5’tiRNA-His-GTG seems to be a responsive process of tumor hypoxic microenvironment, and it is regulated via the HIF1α/angiogenin (ANG) axis." (PMID 33588913, 2021). "Conversely, SIRT3 opposes the Warburg effect via the destabilization of HIF1A, preventing cancer proliferation in glycolytic malignancies, such as breast cancer, acting as a tumor suppressor." (PMID 34831420, 2021). "In fact, HIF-1α has been positively correlated to the ROS level and is suggested to play a crucial role in facilitating tumor progression and metastasis." (PMID 34073079, 2021). "Apparently, stabilization of HIF1a is critical for cancer cells because it induces metabolic adaptations favoring tumor development and progression." (PMID 33673109, 2021). "In present study, we further explored the protective autophagy mediated by LMP1 through ERK/HIF1α/BNIP3 pathway to promote the radioresistance of tumor cells." (PMID 33795637, 2021). "Tumor weights were as follows: HIF-1α-shRNA group: 0.167 ± 0.047 g, NC-shRNA group: 0.260 ± 0.042 g, P = 0.0159." (PMID 34926261, 2021). "In tumours, HIF-1α can trigger the transcription of a series of oncogenes and promote the malignant progression of tumours." (PMID 33639908, 2021). "In tumor models, HIF1α can directly impact apoptosis by upregulating the pro-survival gene myeloid cell leukemia sequence-1 (Mcl-1)." (PMID 34396954, 2021). "In GC patients, long-term hypoxia contributes to HIF-1A activation, which is intricately related to aggressive tumor phenotypes and poor prognosis." (PMID 34604066, 2021). "Hypoxic tumor cells acquire metastatic and lethal phenotypes primarily through the activities of hypoxia-inducible factor 1 alpha (HIF1α)." (PMID 34820369, 2021). "The expression of HIF-1α in tumor tissue as an index of hypoxia was analyzed by western blot, which clearly showed that the expression level of HIF-1α was significantly reduced in the QD-Cat-RGD group compared with the QD-RGD group and control group." (PMID 34887404, 2021). "Hif-1α is the critical player in cell response to hypoxia which triggers transcriptional program that allows them to survive under the harsh tumor microenvironment." (PMID 35011574, 2021). "We have provided further understanding of this process by demonstrating that in HCC, the expression of MOF is inversely related to the expression of HIF-1α, with associated roles for MOF in tumor hypoxia tolerance." (PMID 34540836, 2021). "Within tumor cells, HIF-1α pathway activation aids tumor survival and combats the anti-tumor immune response by upregulating tumor expression of PD-L1 and CD47." (PMID 34868044, 2021). "High PFKFB4 expression assessed by IHC was associated with increased tumor stage and grade, and subsequent in vitro experiments demonstrated that PFKFB4 expression was induced during hypoxia in an HIF-1α-dependent manner." (PMID 33466735, 2021).
tumor (continued). "HIF-1α can regulate glucose metabolism and tumor cell proliferation by regulating other transcription factors." (PMID 34930376, 2021). "We performed immunostaining for HIF-1α in paired primary tumor (n=5) and liver metastasis (n=7), and found increased expression of HIF-1α at the liver metastasis." (PMID 34671197, 2021). "In a xenograft model of colorectal carcinoma HIF-1α knock down by a small interfering RNA was reported to impair tumor growth, while knocking down HIF-2α led to an increase." (PMID 34944758, 2021). "Subsequent studies in mouse models illustrated that in profound hypoxic regions of tumors, HIF-1α upregulates VISTA expression on tumor-infiltrating MDSCs by direct binding to the promoter, thus promoting the immune suppressive function of MDSCs." (PMID 34202979, 2021). "The immunofluorescence of HIF-1α at tumor slices was evaluated after 24 h post intravenous injection of IGM." (PMID 33407570, 2021). "HIF-1α plays a key role in the regulation of tumor progression, metastasis, and recurrence under hypoxic conditions." (PMID 34917132, 2021). "Using pimonidazole immunostaining and expression of HIF-1α and its target genes as hypoxia markers, we investigated the oxygen supply per layer, confirming that multi-layer pNFS induces a hypoxic tumor microenvironment." (PMID 34298763, 2021). "The expression of VEGF can also be promoted through HIF-1α to stimulate angiogenesis in tumor tissues." (PMID 34976809, 2021). "Silencing HIF1A in the Glio-1 or Glio-2 primary cells also restrained tumor growth and significantly extended survival of recipient mice compared to scrambled sh-RNA control cells (Sr-sh)." (PMID 34470658, 2021). "Increased mROS induce and stabilize hypoxia-inducible factor-1 (HIF1a), a transcription factor that enhances the survival and progression of tumors by upregulating genes regulating tumor angiogenesis, metabolism, metastasis, and chemoresistance." (PMID 33673398, 2021). "In contrast to JunB, hypoxia and Hif-1α levels increase in the BM of MM patients during disease progression due to rapidly proliferating tumor cells and promote MM cell dissemination and bone destruction." (PMID 34007044, 2021). "In contrast to other cancers, in ccRCC HIF1α functions as a tumour suppressor by attenuating tumour cell growth, whereas HIF2α promotes tumour development." (PMID 34353313, 2021). "In turn, HIF1α and glycolysis activation contribute to PD-L1 expression and failure of immunosurveillance, as previously observed in other cells in the tumor microenvironment." (PMID 34654454, 2021). "HIF1α is important in tumor initiation and reprogramming of glucose metabolism, while HIF2α regulates biosynthetic pathways such as lipid metabolism, ribosome biogenesis, and transcriptional activity of other factors, such as MYC." (PMID 33803184, 2021). "Hypoxia sensing mainly via HIF-1α has been shown to differentiate MDSCs into macrophages and dendritic cells (DCs), thus altering MDSCs function in the tumor site." (PMID 34202979, 2021). "In tumor-bearing mice administered CaLac by daily subcutaneous injection for 3 weeks, a decrease in tumor volume including the HIF1-α and VEGF deactivation, and suppression of liver metastasis were confirmed." (PMID 33806179, 2021). "Among HIFs, the overexpression of HIF-1α in response to hypoxia promotes tumor blood vessel formation, aggressiveness, metastasis, and drug resistance." (PMID 33946823, 2021). "Subsequently, under the treatment of TGF‐β1, tumour cell CM, hypoxia and Cocl2, HIF‐1α and α‐SMA expression were detected by immunofluorescence in fibroblasts, which showed significant up‐regulated fluorescence intensities." (PMID 33943003, 2021). "This HISLA lncRNA was naturally transmitted from EV to tumour cells where it blocked HIF-1α interaction with prolyl hydroxylase domain 2 (PHD2)." (PMID 33807045, 2021).
tumor (continued). "Samples with low expression of MOF in tumor tissue relative to peritumoral tissue had significantly higher HIF-1α expression, and vice versa." (PMID 34540836, 2021). "In tumor, HIF-1α is known to increase the expression of growth factors such as VEGF-A, -C, and -D and contribute to angiogenesis, lymphangiogenesis, cell survival, invasion and metastasis." (PMID 33466636, 2021). "Among them, HIF1α can affect the formation of many tumours through the mediation of ROS, and HIF2α affect the level of related mitochondrial matrix proteins through oxidative stress." (PMID 34841698, 2021). "In vitro and in vivo experiments showed that HIF-1α transcription was inhibited, the levels of hypoxia-induced factors were reduced, and the anti-tumor effect of gemcitabine was enhanced." (PMID 34809634, 2021). "On the other hand, upregulation of HIF1α also induces TGFβ mediated tumor progression, and both pathways can lead to BC metastasis." (PMID 33917306, 2021). "Then, we used GEPIA to explore the gene expression correlation between LDHA and glycolysis markers, including GLUT-1 (also named SLC2A1) and HIF1A, which play critical roles in glycolysis and tumor microenvironment." (PMID 33902615, 2021). "For example, HIF-1α expression influences the expression of molecules such as PD-L1, leading to the immune escape of tumor cells." (PMID 33807943, 2021). "Nevertheless, HIF-1α remains a viable therapeutic target for modulation, given its key role in tumour growth, invasion and drug resistance." (PMID 34829672, 2021). "More intriguingly, both PRAK and HIF-1α were found to be increasingly expressed in the lung metastatic lesions in comparison to the primary tumors, implying a bias towards higher expression of PRAK and HIF-1α in tumor metastasis." (PMID 33741957, 2021). "Western blotting results confirmed that the expression of APEX1 and HIF-1α was inhibited in tumor tissue." (PMID 33990544, 2021). "Collectively, this study suggests that the HIF1α-dependent suppression of exosome miR101 from hypoxic tumor cells activates macrophages to induce inflammation in the tumor microenvironment." (PMID 34362882, 2021). "HIF-1α follows different pathways to promote tumor drug resistance, and one of them is by regulating MDR-associated proteins such as p-gp and MRP1." (PMID 34680470, 2021). "The activator and inhibitor of PKM2 both promote the anti-cancer immune response and inhibit cancer growth and metastasis by regulating the metabolism of cancer cells and immune cells in the tumor microenvironment through HIF-1α/PKM2 pathway." (PMID 33995634, 2021). "Curiously, this miRNA is a direct HIF-1α target and is upmodulated by hypoxia in both tumor cells and senescent fibroblasts." (PMID 33572359, 2021). "The co-overexpression of PD-L1 and HIF-1α in tumor tissues, for example in hepatocellular carcinoma tissue, is associated with a high risk of recurrence or metastasis." (PMID 34680439, 2021). "A recent study showed that ascorbate inhibits tumor growth of PDAC by reducing the expression of HIF-1α at the protein level under hypoxic condition via post-translational regulation." (PMID 34036383, 2021). "On the contrary, in another study, reduced T cell HIF-1α expression was instead associated with improved CD8 memory cell formation and enhanced anti-tumor cytotoxicity of CD8 T cells." (PMID 34868044, 2021). "So, finding the balance between the pros and cons of targeting HIF-1α and STAT3 can be a direction to solve the problems associated with tumor therapy through modulating the immune response." (PMID 34692527, 2021). "The protective effect of PRAK on metastatic tumor cells was primarily achieved through the promotion of HIF-1α translation." (PMID 33741957, 2021).